GASAL1 (growth arrest associated lncRNA 1)
Synonyms: GASL1
Gene: Long non-coding RNA gene on chromosome 8 (102,804,677 to 102,810,044, forward strand). Ensembl gene ENSG00000253669.
Diseases named in the same sentence as GASAL1 in open-access papers:
GASAL1 is named in the same sentence as 14 diseases in open-access papers, as found by Europe PMC text mining. Sharing a sentence is not in itself a finding about the gene and the disease. The quoted sentences say what the papers report.
tumor (6 papers, 2017 to 2021). "Conversely, growth arrest associated lncRNA 1 (GASL1) has been reported to be significantly downregulated in GC tissues and to inhibit GC cell proliferation and tumor growth by inactivating the Wnt/β-catenin signaling pathway." (PMID 32156253, 2021).
cancer (5 papers, 2017 to 2023). A tumor composed of atypical neoplastic, often pleomorphic cells that invade other tissues. "To explore the critical role of disulfidptosis in cancer and the interactions between disulfide apoptosis and lncRNAs, we identified and validated a set of key lncRNAs associated with disulfidptosis in HCC, including PLBD1-AS1, GASAL1, AC128687.2, MKLN1-AS, AC026412.3, and LINC01269." (PMID 38139458, 2023).
GASAL1 also shares sentences with these, for which no sentence is quoted: chronic heart failure (3 papers); gastric carcinoma (3); lung carcinoma (3); atherosclerosis (2); osteosarcoma (2); esophageal squamous cell carcinoma (1); heart failure (1); hepatocellular carcinoma (1); intracranial aneurysms (1); liver cancer (1); papillary thyroid carcinoma (1); vascular disorder (1).